IL6 (interleukin 6)
Diseases named in the same sentence as IL6 in open-access papers (continued):
Sharing a sentence is not in itself a finding about the gene and the disease.
cancer (continued). "After adjustment for conventional risk factors, only IL-6 (HR 1.51, 95% CI 1.18-1.95) and sTNFR2 (HR 3.27, 95%CI 1.65-6.47) predicted cancer development." (PMID 24205276, 2013). "Cygb loss has been reported to be associated with increased cancer cell proliferation, elevated extracellular signal–regulated kinase and Akt activation, overexpression of interleukin-6 (IL-6)." (PMID 23688241, 2013). "The enhanced adipogenesis and the pro-metastatic properties were conferred by the high levels of IL-6 secretion by cancer-associated MSCs and were reversible by functionally inhibiting of IL-6." (PMID 23977098, 2013). "Conversely, the functional blocking of IL-6 with an anti-IL-6 antibody significantly prevented the differentiation of cancer-associated 3A6PC3 into adipocytes." (PMID 23977098, 2013). "We also found that IL-6 is a direct target gene for the let-7 microRNA, which was downregulated in cancer-associated MSCs." (PMID 23977098, 2013). "Among 174 cytokines were tested, IL-6, was significantly higher in all three of the cancer-associated 3A6 derivatives compared with 3A6RWV." (PMID 23977098, 2013). "To elucidate the mechanism by which cancer cells activate fibroblasts, we examined the signal transduction pathways associated with IL-6 expression by immunoblot analysis." (PMID 23593346, 2013). "We analyzed DNA methylation after treatment with IL-6, a well-known stimulator of fibrinogen expression and a cytokine associated with changes in DNA methylation levels in cancer." (PMID 23991173, 2013). "In several cancers, including PCa, IL6 is implicated in the development and progression of the disease." (PMID 23913484, 2013). "Exposure of DCs to mafosfamide (MAFO)-treated cancer cells causes phenotypic maturation of DCs and their functional stimulation, characterized by the release of various cytokines (IL-1β, IL-6, IL-12)." (PMID 24376443, 2013). "In particular, IL-6 has been reported to be deeply involved in inflammation associated with cancer development and progression." (PMID 23840274, 2013). "In our study, we demonstrated that IL-6 is an independent risk factor of cancer-related mortality in older adults with a longer mean follow-up period and fewer percentages of diabetics, smokers, and obese participants." (PMID 22514624, 2012). "In separate analyses using tertiles, high IL-6 levels was associated with a statistically significant increased risk of cancer mortality in unadjusted, and age-sex adjusted models." (PMID 22514624, 2012). "Results remained consistent serum IL-6 associated with cancer mortality in unadjusted, age-sex adjusted, and multivariable adjusted models." (PMID 22514624, 2012). "Selumetinib has also been shown to inhibit secretion of cytokines such as IL-6, IL-1β and tumour necrosis factor-α, which are implicated in the promotion of cancer cachexia." (PMID 22510747, 2012). "Serum IL-6 was associated with 74% excess risk of cancer mortality after excluding participants with cancer at baseline." (PMID 22514624, 2012). "Tumor-cell-associated NF-κB and its regulated genes, such as the cytokine IL-6, have been linked to the development of chemoresistance in several types of cancers." (PMID 23028510, 2012). "More recently, the PROSPER study showed that high IL-6 levels was associated with an increased risk for cancer incidence and cancer-related mortality in 5,804 elderly participants." (PMID 22514624, 2012). "Together, the data suggest that IL-6 signal transducer gp130 is an essential prerequisite for long-term mechanical hypersensitivity associated with cancer, inflammation and nerve injury." (PMID 21951917, 2011). "Together, the results argue for IL-6 signal transducer gp130 as an essential prerequisite in nociceptors for long-term mechanical hypersensitivity associated with cancer, inflammation and nerve injury." (PMID 21951917, 2011).
cancer (continued). "In cancer patients, skeletal muscle wasting, weight loss and mortality are all positively associated with increased serum cytokines, particularly Interleukin-6 (IL-6), and the presence of the acute phase response." (PMID 21799891, 2011). "Consistent with a causative role in muscle wasting in humans, circulating IL-6 has been reported to be a marker of weight loss in patients afflicted by various forms of cancer." (PMID 21799891, 2011). "In this study, we address the importance of the polymorphisms IL–6 GC–174, IL–10 G–1082, C–819, C– 592, which are known to affect the transcription levels of the genes and are also known to be important for cancer cell growth." (PMID 22567049, 2011). "Published reports have implicated both Twist and IL-6 in the development/progression of cancer, as their expressions are detectable in many epithelial tumors or patients' serum and are associated with unfavorable clinical outcomes." (PMID 21559372, 2011). "High serum IL-6 levels correlate with poor disease outcome and reduced clinical prognosis in patients with breast, lung, and liver cancer and with cancer formation in a murine colitis-associated colon cancer model." (PMID 21967801, 2011). "Interleukin-6 is implicated in the pathogenesis of cancer-associated weight loss, driving lipid catabolism and muscle protein catabolism, perhaps through both lysosomal (cathepsin) and non-lysosomal (proteasome) pathways." (PMID 20502713, 2010). "Experimentally, IL-6 has been implicated as a promoter of cancer growth by enhancing colony formation of human colon carcinoma cells in a dose-dependent manner in vitro." (PMID 20823887, 2010). "Spontaneous interleukin-6 (IL-6) production has been observed in various tumors and implicated in the pathogenesis, progression and drug resistance in cancer." (PMID 21122157, 2010). "Apart from the production of myeloid growth factors, cancer inflammation and associated neutrophilia have also been associated with the release of IL-6 (interleukin-6) and TNF-α (Tumour necrosis factor-α)." (PMID 20053279, 2010). "The most prominent cytokines that have also been shown to be linked with cancer development were IL-6, IL-8 (CXCL8), GRO/GRO-α (CXCL1), GCP-2 (CXCL6), and TIMP-1." (PMID 20723242, 2010). "Elevated serum levels of IL-6 are often associated with the pathogenesis of many cancers, including those of the pancreas and breast." (PMID 19712481, 2009). "Increases in cancer invasion and staging are generally associated with increases in preoperative serum IL-6 levels." (PMID 19457231, 2009). "Two previous studies examined the effect of an anti-IL-6 in association with cisplatin on cancer cells." (PMID 19956602, 2009). "In terms of survival rate and time to cancer progression, the results of this study showed that IL-6 levels were associated with poor prognoses." (PMID 19457231, 2009). "It has been confirmed that the IL-6 gene polymorphisms play an important role in the development of cancer cachexia, and the polymorphism of IL-1 β is associated with the cachexia from locally advanced gastric cancer." (PMID 20037740, 2009). "These questions can only be answered when more information on polymorphic sites and cancer-related mutations in the IL-6 gene will be available." (PMID 18205904, 2008). "In cancer patients, the rates of production of IL-6 from isolated PBMCs can be linked to markers of systemic inflammation such as CRP." (PMID 17088911, 2006). "High serum levels of IL-6 have been associated with advanced stage disease and worse prognosis for several cancer types including ovarian, breast and colorectal." (PMID 14735187, 2004). "TNF-α is a pleiotropic cytokine, which like IL-6 has been shown to be associated with cancer progression." (PMID 15150588, 2004). "Cancer‐associated fibroblasts (CAFs) are the main source of IL‐6." (PMID 40968783, 2026).
cancer (continued). "Chen et al110 recently reported that lysine-specific demethylase 2A (KDM2A) expression can be stimulated in normal fibroblasts by cancer-derived cytokines, including IL-6; this results in the transformation of these fibroblasts into cancer-associated fibroblasts (CAFs)." (PMID 40584290, 2025). "Therefore, the main objective of this study was to examine the impact of IL-6 levels measured in the peripheral blood of cancer patients before and after ICI initiation on the risk of developing irAEs." (PMID 41019062, 2025). "The downregulation of COX-2 and interleukin-6 (IL-6) suggests that BT may exert anti-inflammatory effects, reducing the risk of chronic inflammation and subsequent skin damage or cancer development." (PMID 40870975, 2025). "Although the causal relationship between anti-IL-6 agents and the risk of developing malignant tumors is unknown, one report shows that 10–20% of patients with NMOSD had a pre-onset history of malignant tumor." (PMID 39470886, 2025). "The excessive production and signaling disorder of IL-6 are associated with various cancers." (PMID 40118853, 2025). "Additionally, upon analyzing the transcriptional changes that occur in these cells after stimulation, we observed a downregulation of several oncogenes and cancer-associated genes, including IL6, MMP2, and CCND2." (PMID 40043049, 2025). "Furthermore, the oncoprotein LMP1 transforms fibroblasts into cancer‐associated fibroblasts (CAFs), which secrete cytokines and chemokines (including IL‐6, IL‐8, CXCL10, and TGF‐β) to alter cancer cell metabolism." (PMID 40365984, 2025). "The fact that CRP, which is regulated by IL-6, rises with IL-6 may be part of the mechanism by which high levels of CRP are associated with poor prognosis in cancer patients." (PMID 40115790, 2025). "Interleukin-6 (IL-6), a pro-inflammatory cytokine involved in the inflammatory phase of wound healing, has been implicated in cancer development and progression through chronic inflammation and activation of the JAK/STAT pathway, which supports cell proliferation and survival." (PMID 39833941, 2025). "IL6-associated pathways (e.g., focal adhesion, cytoskeleton regulation) were enriched (GeneRatio = 0.03–0.05), with miR-146a-5p targeting genes in endocytosis and proteoglycans in cancer, suggesting roles in immune dysregulation and implantation failure." (PMID 41227338, 2025). "Similarly, IL-6 has been linked to the development and progression of BC, with the IL-6 signaling pathway activated in cancer cells during cancer cell growth, angiogenesis, invasion, metastasis, and chemoresistance." (PMID 39896297, 2025). "Key cytokines implicated in cancer cachexia include IL-6, TNF-α, TGF-β, INF-γ and MIC-1/GDF15." (PMID 40519290, 2025). "The combination of IL-6 <185 pg/mL and IL-10 <20 pg/mL identified low-risk patients with a septic shock rate of only 0.7%, suggesting these cytokines enable early risk stratification in febrile pediatric cancer patients." (PMID 40647525, 2025). "Cancer-associated fibroblasts promote metastasis by secreting cytokines, such as IL-6." (PMID 39956902, 2025). "Next, we grouped them into cytokines associated with pre-cancer or the initiation stage of HCC (IL-6, TGF-β, MCP-1, FGF2, IL-2, IL-8, IL-12p40, IL-12p70, IL-18, IP-10, TNF-α, and IFN-γ), the early stage of HCC (OPN, GDF-15, RANTES, and VEGFA), and the advanced stage of HCC (IL-10, and MIP-3)." (PMID 41219858, 2025). "Elevated IL-6 levels are associated with weight loss and reduced survival in cancer patients." (PMID 40519290, 2025). "The IL-6/STAT3 signaling pathway is critical for cancer cachexia-induced muscle loss." (PMID 40869331, 2025). "Muscle loss may exacerbate cancer-related inflammation, elevated inflammatory factors such as interleukin-6 and tumor necrosis factor-α may lead to immunosuppression." (PMID 40904512, 2025).
cancer (continued). "Additionally, cancer-derived interleukin-6 (IL-6) activates KDM2A in cancer-associated fibroblasts via the STAT3/NF-κB p50 pathway, promoting stromal-mediated resistance." (PMID 40941035, 2025). "Taking into consideration that high levels CRP were found to be strongly associated with cancer severity, salivary IL-6 and CRP, along with miR-320a, could be used as indicators for healthy mucosa transition to OLP and, further, to OSCC." (PMID 41303164, 2025). "IL-6 expression had been proved to be associated with irAEs occurrence in some types of cancers." (PMID 40519900, 2025). "RASGRP1 (RAS guanyl releasing protein 1), a bi-functional regulator that promotes acute inflammation and inhibits inflammation-associated cancers, can inhibit the growth of inflammation-associated tumors and activate inflammatory response by sponging let-7a to promote IL-6 expression." (PMID 40861815, 2025). "However, persistently elevated IL-6 levels are associated with chronic inflammation, autoimmune diseases, and cancer progression." (PMID 40650089, 2025). "Consequently, IL-6 is associated with poor outcomes in cancer patients and is linked to adverse outcomes of immunotherapy." (PMID 41051603, 2025). "IL-6 is also involved in chronic low-grade inflammatory states associated with non-communicable diseases, including atherosclerosis, type 1 and 2 diabetes, osteoporosis, Alzheimer’s disease, and cancer." (PMID 41155261, 2025). "Due to its modulatory effect on inflammation, IL-6 is associated with cancer development." (PMID 39941741, 2025). "Similarly, IL-6/IL-11 signaling in cancer-associated fibroblasts (CAFs) induces STAT3 activation, creating a protumorigenic niche that drives CRC growth and correlates with dismal outcomes." (PMID 40963625, 2025). "Additionally, COL6A1 is packaged into osteosarcoma-derived exosomes, which convert normal fibroblasts into cancer-associated fibroblasts (CAFs) that secrete IL-6 and Interleukin-8 (IL-8)." (PMID 40940809, 2025). "Understanding the regulation and activation of IL6, particularly in the context of cancer, could provide valuable insights for improving diagnostic procedures and developing targeted treatments." (PMID 40427188, 2025). "In this context, by measuring IL6 levels alongside other potential risk factors and cancer-related inflammatory mediators, IL6 could serve as an effective “screening and diagnostic” biomarker for OC." (PMID 40427188, 2025). "Additionally, cancer‐associated fibroblast‐derived MSI2 facilitates NSCLC metastasis by inducing epithelial–mesenchymal transition via paracrine IL‐6 signaling." (PMID 39969091, 2025). "•PIS is often caused by the systemic production of IL-6 by cancer cells." (PMID 39754984, 2025). "Interestingly, multiple studies suggest IL-6 is associated with increased PD-L1 expression through various signaling pathways, promoting immune evasion in multiple cancer types (31, –, 33)." (PMID 39927795, 2025). "Furthermore, the presence of HPV-induced inflammatory cytokines such as interleukin-6 (IL-6) and interleukin-8 (IL-8) has been implicated in promoting a pro-inflammatory environment conducive to cancer development." (PMID 39338421, 2024). "A high circulating level of IL-6 is associated with a risk of cancer incidence and poor prognosis." (PMID 39337548, 2024). "Elevated IL-6 levels have been associated with poorer outcomes in cancer patients, but its specific role in modulating responses to ICIs remains unclear." (PMID 39766045, 2024). "IL-6 is associated with both an increased irAE risk and inferior cancer-related outcomes." (PMID 39403935, 2024). "highlighted those related genes highly expressed in the high-risk subtype showed significant enrichment in multiple cancer-related pathways such as IL6-JAK-STAT3 signaling, Wnt-β-catenin signaling, Kras signaling and IL2-STAT5 signaling based on the TCGA cohort and Meta cohort." (PMID 38993563, 2024).
cancer (continued). "The stimulation of PPAT exosomes by PC-3 CM induced the secretion of the bone-bridging protein, TNF-α, and IL-6, which are associated with cancer progression, upregulation of bone-bridging protein expression by 13-fold, and decreased expression of the protective adipokine lipocalin." (PMID 38164282, 2024). "Cancer cells release exosomes containing IL6 and miRNAs, which modify cancer-associated adipocytes." (PMID 38714880, 2024). "To investigate whether AP neurons mediate the functions of IL-6 in the development of cancer cachexia, we sought to suppress Il6ra, the gene encoding IL-6Rα, in these neurons using a recently developed CRISPR/dCas9 interference system." (PMID 38824130, 2024). "The IL-6 cytokine plays a pivotal role in the modulation of immune responses and is implicated in the pathogenesis of various diseases, including autoimmune disorders, chronic inflammatory conditions, and cancer." (PMID 38397603, 2024). "Finally, models excluding cancer grade and hormone receptor status variables showed consistency in the results, particularly regarding the association between IL-6 and all-cause mortality." (PMID 39342063, 2024). "Our study identifies a central mechanism underlying the function of peripheral IL-6, which may serve as a target for treating cancer cachexia." (PMID 38824130, 2024). "Likewise, several inflammatory markers (such as IL-1 and IL-6) have been shown to be associated with the development and progression of cancer and have therefore also become targets for cancer treatment." (PMID 39492450, 2024). "We demonstrate an organic electrochemical transistor(OECT) biosensorfor the detection of interleukin 6 (IL6), an important biomarker associatedwith various pathological processes, including chronic inflammation,inflammaging, cancer, and severe COVID-19 infection." (PMID 38141020, 2024). "Moreover, IL-6 was associated with decreased objective response rate and worse cancer-specific and all-cause mortality." (PMID 39403930, 2024). "Given that TGF-β, IL-1β and IL-6 are essential for Th17 cell differentiation, the connection between neutrophilic asthma (characterized by high levels of these cytokines) and metabolic dysregulation and the risk of cancer becomes apparent." (PMID 38629073, 2024). "IL-6 is one of the most potent inflammatory cytokines implicated in various pathophysiological responses and diseases, from the response to infectious agents to CV, kidney, rheumatic, and cancer." (PMID 39184952, 2024). "High expression of IL6 was associated with reduced cancer-specific survival (p = 0.025)." (PMID 39766336, 2024). "IL-6 levels were also associated with inferior cancer-specific survival and overall survival." (PMID 39403935, 2024). "Local or systemic overexpression of the gene encoding IL-6 has been found in cancer patients." (PMID 38534756, 2024). "Furthermore, in CRC stroma, cancer-associated fibroblasts (CAFs) produce IL-6 which upregulates the expression of metastasis-associated markers such as Leucine Rich Alpha-2-Glycoprotein 1(LRG1) via the JAK2/STAT3 signaling." (PMID 38520006, 2024). "Pro-inflammatory cytokines such as TNF-α and IL-6 are linked to cancer." (PMID 39120359, 2024). "Single-cell RNA sequencing revealed an increase in inflammatory cancer-associated fibroblasts (iCAF), M2 macrophages, and a decreased dendritic cell (DC) quality that ultimately resulted in a highly immunosuppressive microenvironment driven by IL6+ iCAFs." (PMID 38727236, 2024). "Indeed, levels of H3Cit in cancer patients have been shown to have a positive association with TNFα, IL-6, and IL-8, indicating a relationship between the expression of these pro-inflammatory cytokines and the release of H3Cit." (PMID 38744744, 2024).